PROM1 (prominin 1)
Diseases named in the same sentence as PROM1 in open-access papers (continued):
Sharing a sentence is not in itself a finding about the gene and the disease.
leukemia (62 papers, 2006 to 2026). A malignant (clonal) hematologic disorder, involving hematopoietic stem cells and characterized by the presence of primitive or atypical myeloid or lymphoid cells in the bone marrow and the blood. "PROM1 expression was significantly increased in CD19+ bone marrow blasts from mice with CRISPRKMT2A::AFF1 leukemia compared to Cas9-only controls (P = .02), and correlated strongly with CD133 cell surface protein expression as measured by flow cytometry." (PMID 40609078, 2025). "Leukemias in the Cas9 control mice had a similar proportion of CD133+ blasts at cull as the original leukemia, but leukemias derived from PROM1 KO blasts also demonstrated some CD133 positivity at the point of culling." (PMID 40609078, 2025). "PROM1 KO or Cas9-only control CRISPRKMT2A::AFF1 blasts were also transplanted into NSG mice 12 to 18 hours after KO (n = 2 CRISPRKMT2A::AFF1 leukemias, 12 mice)." (PMID 40609078, 2025). "From this perspective, prolonged inhibition of DOT1L seems to favor KMT2A-rearranged leukemia cells that completely lack PROM1/CD133 but do display LILRB4/CD85k and CD33 expression." (PMID 37740239, 2023). "To better understand the role of PROM1/CD133 in MLLr leukemias, we have systematically characterized the structure of the PROM1 gene locus and the mechanism of PROM1/CD133 regulation for the first time." (PMID 32242051, 2021). "This is consistent with a permissive environment for MLL-AF4 binding at PROM1, if the leukemia was initiated in any of these cell types." (PMID 32242051, 2021). "To understand how PROM1 expression is regulated in CD133+ MLLr leukemias, we analyzed ChIP-seq datasets from multiple cell types, using MLL-N and AF4-C binding as a proxy for MLL-AF4 fusion protein binding." (PMID 32242051, 2021). "In contrast, we find that in CD133-negative leukemia cells the PROM1 promoter is bound by components of the polycomb repressive complex 2 (PRC2) and this is associated with a lack of enhancer features, including enhancer–promoter interactions." (PMID 32242051, 2021). "Understanding these mechanisms is likely to be key to the future development of PROM1/CD133-directed therapeutic targeting in these leukemias." (PMID 32242051, 2021). "In MLL-AF4 B-cell acute lymphoblastic leukemia (ALL or B-ALL), the expression of the PROM1 gene encoding a specific marker (CD133) is regulated by MLL-AF4 and has proven to be a good target for the treatment of MLL-r leukemia." (PMID 33302406, 2020). "From these data we conclude that the presence of an MLL-FP or EZH2/H3K27me3 at the PROM1 promoter may determine whether it is expressed in leukemia cells." (PMID 32242051, 2021). "Prominin-1 (CD133) is regarded as a tool for hematopoietic stem cell isolation as well as an identification marker for targeting populations of malignant transformation in certain cancers such as leukemia." (PMID 34207434, 2021). "As observed, not all MLLr leukemias are CD133+, and the mechanism of differential PROM1 regulation in leukemia is unknown." (PMID 32242051, 2021). "CD133, encoded by the PROM1 gene, is a pentaspan transmembrane glycoprotein of great potential value as a pan-cancer target as it is commonly associated with cancer stem cells in multiple different tumor types, including leukemia." (PMID 32242051, 2021). "Finally, as in the CD133-negative leukemia cells, the PROM1 promoter was marked by H3K27me3 in CD34− FBM and FL, consistent with its repression by PRC2." (PMID 32242051, 2021). "Histone H3 lysine-79 (H3K79) methylation was first identified to be a regulator of PROM1 gene expression in an investigation aimed at identifying targets of mixed lineage leukemia (MLL) fusion proteins responsible for aberrant gene expression in patients with leukemia." (PMID 38532366, 2024).
leukemia (continued). "One of the most attractive features of PROM1/CD133 as a potential therapeutic target derives from the recognition that the gene is a direct target of MLL-AF4 regulation, suggesting that in MLLr leukemias PROM1/CD133 expression is tightly linked to the activity of the fusion protein itself." (PMID 32242051, 2021). "Thus, the balance between Trithorax and polycomb group proteins at PROM1 upon leukemia initiation may render CD133 either highly expressed or absent." (PMID 32242051, 2021). "PROM1, FLT3, CTGF, LGALS1, IGFBP7, ZNRF1, and RUNX2 were found highly expressed in the MLL-R pro-B ALL compared to the other subclassification of leukemia." (PMID 36276286, 2022). "For instance, in CD133− leukemia cell lines such as THP1 and RCH-ACV, the promoter of PROM1 is bound by EZH2 (the enzymatic component of PRC2) and marked with H3K27me3, suggesting that the gene is polycomb-repressed." (PMID 32242051, 2021). "PROM1 is a commonly used stem cell and cancer stem cell marker, and MLL-AF4 was shown to promote PROM1 transcription, which is required for MLL-AF4-driven leukemia cell growth (Mak, Nixon & Moffat, 2012)." (PMID 31523525, 2019). "PROM1 promoter repression by polycomb repressive complex 2 (PCR2) in CD133-negative leukemia cells impair the interaction between the PROM1 promoter and the intragenic PROM1 and TAPT1 enhancers, explaining the absence of CD133 expression." (PMID 37922108, 2024). "In keeping with previous findings, MLLr leukemia cells were found to express PROM1 at much higher levels than the non-MLLr cohort." (PMID 32242051, 2021). "Strikingly, whilst MLL-AF4 and MLL-ENL ALL samples displayed high levels of PROM1 expression, other fusion proteins, including MLL-AF9, were associated with lower levels of expression, more comparable to non-MLLr leukemias." (PMID 32242051, 2021). "In order to model PROM1/CD133 behavior and regulation, we first evaluated CD133 expression by flow cytometry to identify CD133-positive and -negative leukemia cell lines." (PMID 32242051, 2021). "The reason why PROM1 is PRC2 repressed in some cell types and expressed in others, and whether the same mechanism drives repression in CD133− primary ALL patient samples is unknown, but may reflect the developmental stage of the cell of origin in different leukemias." (PMID 32242051, 2021). "Taken together, these data indicate that although a CD133+ immunophenotype is not restricted to MLLr ALL, PROM1/CD133 is aberrantly expressed in a large subset of cell lines and MLLr leukemia patients, particularly those associated with MLL-AF4 and MLL-ENL fusion proteins." (PMID 32242051, 2021). "To assess whether PRC2 silencing is a common mechanism for PROM1 regulation in CD133-negative leukemia and not restricted to MLL-AF9 AML, we analyzed RCH-ACV (non-MLLr Pre-B-ALL) and ML-2 (MLL-AF6 AML) cell lines, which do not express PROM1 or present CD133 on the cell surface." (PMID 32242051, 2021). "Alternatively, differences in the chromatin state at PROM1 may render the environment permissive for MLL-FP spreading only in certain target cell types, so leukemias that initiate in a PROM1-repressed environment may not be capable of reactivating the locus." (PMID 32242051, 2021).
non-small cell lung carcinoma (59 papers, 2008 to 2025). A group of at least three distinct histological types of lung cancer, including non-small cell squamous cell carcinoma, adenocarcinoma, and large cell carcinoma. "Recent studies suggest that PROM1 is upregulated in non-small cell lung cancer tissue compared to normal lung tissue, and mutations in PROM1 are associated with poor prognosis." (PMID 31164716, 2020).
neuroblastoma (51 papers, 2009 to 2026). Neuroblastoma (NB) is the most common solid, extracranial childhood tumor. "In contrast, the expression of PROM1, SOX2, and NESTIN, three neuroblastoma stem cell markers, exhibited a notable increase in all iLIN28B samples compared to their corresponding CTRLs." (PMID 40679030, 2025). "By 5 days in 3D cultures, neuroblastoma cells in collagen gels showed up-regulation of neuronal markers and PROM1 (CD133, prominin) and slight down-regulation of glial markers (e.g. OLIG2 and GFAP) in 3D as compared to 2D." (PMID 32321995, 2020).
brain cancer (47 papers, 2006 to 2025). A primary or metastatic malignant neoplasm affecting the brain. "Prominin-1 (PROM1; also called CD133) is a marker of cancer stem cells in many types of cancer, including human brain cancer." (PMID 35970913, 2022). "These issues have led to the generation of contradictory data and discussions and should be kept in mind when addressing prominin-1 in normal and pathological conditions such as brain cancer." (PMID 34476215, 2021). "CD133 (prominin-1) is one of the earliest stem-cell surface markers used for identification and isolation of cancer stem cells in malignant brain tumors." (PMID 26977157, 2016). "Various prognostic markers have recently been evaluated, including the stem cell marker CD133 (Prominin-1), which was reported to be a cancer stem cell marker for cancers of the brain, colon, prostate, liver, lung, kidney, ovaries, and skin." (PMID 23448401, 2013). "The fraction of tumor cells expressing CD133 (Prominin-1), a marker for both neural stem cells and brain cancer stem cells, display strong capability on tumor's resistance to chemotherapy including temozolomide." (PMID 23183822, 2012). "The transmembrane protein CD133 (Prominin-1 or AC133) is one of the markers that was first used to identify and isolate stem cells in brain cancers." (PMID 21694723, 2011). "This idea was pioneered by Bao and collaborators in glioblastoma multiform (GBM) where cells expressing CD133 (Prominin-1), a marker for both neural stem cells and brain cancer stem cells, preferentially activate the DNA damage checkpoint in response to radiation." (PMID 24681585, 2014). "The surface molecule CD133, also known as AC133 and prominin-1, is expressed on normal stem cells and on CSCs identified in a range of cancers, including cancer of the brain, colon, pancreas and liver." (PMID 22612877, 2011). "Here, we identified in human brain cancer samples a subpopulation of malignant cells expressing the stem marker Prominin-1 and characterized by a non-cycling transcriptome signature." (PMID 35970913, 2022). "The tumor initiation, maintenance and proliferation properties conferred by SOX2 may also introduce drug-resistance to CD133 (prominin-1) positive CSCs in GBM, making SOX2 a therapeutic target to treat the lethal brain cancer." (PMID 32092088, 2020). "Additionally, our studies suggest that the ALDHbright population validates the CSC phenotype based on the increased expression of brain cancer stem cells genes such as ALDH1A1, ITGA6, THY1, PROM1, and SOX2." (PMID 30646520, 2019).
medulloblastoma (41 papers, 2009 to 2024). A malignant, invasive embryonal neoplasm arising from the cerebellum. "High levels of PROM1 mRNA are also associated with poor prognosis in pediatric medulloblastoma." (PMID 31164716, 2020). "Notably, ZNF157 was predominantly amplified in the PROM1-centered gene set and this gene has been shown to be epigenetically regulated in medulloblastoma." (PMID 31164716, 2020). "Furthermore, we identified retina specific interphotoreceptor matrix proteoglycan 2 (IMPG2), phosducin (PDC) and prominin 1 (PROM1) as upregulated genes in the RB tumor group, which are all related to CRX expression in medulloblastoma." (PMID 39695086, 2024).
colorectal tumors (36 papers, 2008 to 2025). "The findings of these studies collectively suggest that ISG15 expression may be involved in the PROM1-positive to PROM1-negative transition of CSCs in colorectal tumors." (PMID 27626310, 2016).
endometrial cancer (31 papers, 2010 to 2025). Primary or metastatic malignant neoplasm involving the endometrium (mucous membrane that lines the endometrial cavity). "Endometrial carcinoma-derived stem-like cells (ECSCs) are commonly identified using specific cell surface markers, such as CD44-antigen (CD44) and Prominin-1 (CD133), as their expression is associated with tumorigenicity, invasiveness and metastasis." (PMID 35269569, 2022). "In endometrial cancer, specific cell surface markers, including CD44-antigen (CD44) and prominin-1 (CD133), have been identified as surrogate markers for CSCs." (PMID 38539419, 2024).
sarcoma (31 papers, 2008 to 2025). A usually aggressive malignant neoplasm of the soft tissue or bone. "In summary, our work showed that EMX1 and EMX2 act as tumor suppressors by suppressing the activity of stem cell regulatory genes (OCT4, KLF4, MYC, SOX2, NANOG, NES, and PROM1) in sarcoma." (PMID 34016958, 2021). "In summary, our work shows that EMX1 and EMX2 act as tumor suppressors by suppressing the activity of stem cell regulatory genes (OSKM, NANOG, and PROM1) and effectors of the canonical Wnt pathway (CTNNB1, TCF4, MYC, WNT1 and CCDN1) in sarcoma." (PMID 34364391, 2021). "Our work showed that EMX1/EMX2 act as tumor suppressors in sarcomas by repressing the activity of stem cell regulatory genes (OCT4, SOX2, KLF4, MYC, NANOG, NES, and PROM1)." (PMID 34016958, 2021). "CD133, also known as prominin-1, is a membrane protein considered as putative CSC marker in various cancers, including sarcomas, at least in early studies." (PMID 32532153, 2020). "CD133 is a transmembrane glycoprotein, also known as AC133 or prominin-1, which is used as a cellular marker of cancer stem cells (CSCs) in many different malignancies, including sarcomas." (PMID 34440182, 2021). "Although the first studies suggested prominin-1 (CD133) or nestin as rhabdomyosarcoma CSC markers, our recent study showed that, regardless of these proteins, only sarcoma cell lines that express high levels of the transcription factor SOX2 form tumors in immunodeficient NOD/SCID gamma (NSG) mice." (PMID 31941033, 2020).
thyroid cancer (29 papers, 2009 to 2026). "We identified that PROM1 expression was higher in BRAF-mutated tumors in males within the TCGA Thyroid Cancer database, which may be partly why CD133 expression and prognosis differ in males." (PMID 40214912, 2025). "The 6-SNP PRS-based model is composed of DIRC3_rs6759952, GAP43_rs13059137, NRG1_rs7834206, PROM1_rs72616195, LOC100507065_rs11175834, and LRP1B_rs1369535, that is, SNPs related to cell growth and inflammation were found to be positively associated with the risk of thyroid cancer." (PMID 33805984, 2021). "Additionally, research in thyroid cancer has shown that its expression varies across different subtypes and that a specific gene signature, including high PROM1 expression, correlates with worse recurrence-free survival." (PMID 40650074, 2025). "PROM1, also known as CD133, is a pentaspan transmembrane glycoprotein that promotes tumor initiation by thyroid cancer stem cells and suppresses cancer cells’ differentiation and helps maintain stem cell properties." (PMID 33805984, 2021).
bladder cancer (28 papers, 2013 to 2026). "In the sEV fractions, PROM1 was downregulated in bladder cancer patients." (PMID 37371512, 2023).
lung adenocarcinoma (28 papers, 2013 to 2025). A carcinoma that arises from the lung and is characterized by the presence of malignant glandular epithelial cells. "The authors reported that cancer cells obtained from peripheral blood of patients with lung adenocarcinoma displayed a cancer-stem-cell-related phenotype (expression of P-glycoprotein 1 (CD44), prominin-1 (CD133), and aldehyde dehydrogenase)." (PMID 34834295, 2021).
retinal degeneration (27 papers, 2007 to 2025). Degeneration of the retina. "PDC modulates G-protein-coupled receptor signaling, and Prom1 mutations link to retinal degeneration." (PMID 39534499, 2024). "Profound degeneration of the outer retinal layer, accompanied by extensive loss of RPE cells, was consistent with the longitudinal progression of Prom1-associated retinal degeneration." (PMID 39513868, 2024). "Defective RPE autophagy is also a well-established mechanism of disease in age-related macular degeneration (AMD) in numerous published models, as well as Stargardt Disease and PROM1-associated retinal degeneration." (PMID 38920696, 2024). "CD133 is present on photoreceptor cells throughout human life, and mutations in the PROM1 gene are associated with retinal degeneration leading to blindness." (PMID 38139228, 2023). "All patients diagnosed with PROM1-related retinal degeneration harbored the heterozygous missense variant p.R373C (NM_006017.2:c.1117C > T), which presented an autosomal dominant inheritance pattern." (PMID 38072963, 2023). "Although studies have investigated PROM1-related retinal degeneration in various populations, few have focused on the genetic variants and clinical characteristics of PROM1-associated retinal degeneration within the Asian population." (PMID 38072963, 2023). "The study identified seven patients from five unrelated families with PROM1-related retinal degeneration, all carrying the autosomal dominant variant PROM1 p.R373C; no other PROM1 gene variants were detected." (PMID 38072963, 2023). "This study aimed to bridge this knowledge gap by investigating the spectrum of genetic variants in PROM1-associated retinal degeneration and to provide an understanding of the overall clinical picture of this condition in the Korean population." (PMID 38072963, 2023). "Mutation in the Prom1 gene in humans and animal models are associated with several forms of retinal degeneration." (PMID 36215230, 2022). "The forms of retinal degeneration associated with PROM1 mutations represent a diverse spectrum in terms of disease onset and severity of the presented symptoms." (PMID 36215230, 2022). "This study shows that PROM1 recessive variants were associated with early-onset, severe retinal degeneration, whereas the c.1117C>T variant, which was associated with autosomal dominant inheritance, showed a milder, cone-driven phenotype." (PMID 31199449, 2019). "In previous studies using Prom1 gene deficient mice (Prom1KO), progressive retinal degeneration in the postnatal stages has been demonstrated." (PMID 31685837, 2019). "Of note, mutations in human EYS and PROM1 cause several forms of retinal degeneration including autosomal recessive retinitis pigmentosa, rod-cone dystrophies and cone-rod dystrophy." (PMID 25412384, 2014). "First, recessive and dominant mutations in the PROM1 gene cause inherited retinal degeneration including retinitis pigmentosa, macular degeneration and cone-rod dystrophy." (PMID 21407811, 2011). "For instance, patients that harbor mutations in the prominin-1 gene suffer from retinal degeneration." (PMID 20808829, 2010). "It is a very useful marker for various stem cells and can be found in a wide variety of differentiated epithelium and non-epithelial cell types, including photoreceptor cells of invertebrate where mutations in the PROM1 gene are associated with various forms of retinal degeneration." (PMID 37103345, 2023). "We here analysed early events associated with retinal degeneration in Prom1-KO mice." (PMID 34664634, 2021). "As genetic deletion of Prom1 causes significant neural defects, such as retinal degeneration, a reduction in the number of neurons in the brain, and walking problems, Prom1 might have specific roles in neuronal tissues." (PMID 33446881, 2021).